IL10 (interleukin 10)
Diseases named in the same sentence as IL10 in open-access papers (continued):
Sharing a sentence is not in itself a finding about the gene and the disease.
meningioma (5 papers, 2020 to 2025). A generally slow growing tumor attached to the dura mater. "Earlier investigations have demonstrated that increased IL-10 within the tumor microenvironment, including meningiomas, is associated with a poorer prognosis, highlighting the crucial role of inflammatory factor regulation in the pathophysiology of meningioma." (PMID 37425011, 2023). "At the same time, we detected greater IL-10 secretion by macrophages cocultured with meningioma cells by ELISA." (PMID 35637794, 2022). "The levels of the cytokines IL-6, IL-10, and GM-CSF, as well as the levels of the chemokine CCL2, were analyzed in the plasma of 27 patients with meningiomas (since one case had an undetermined subtype)." (PMID 38259646, 2023). "Comparison of the AKT1 E17K and NF2-negative mRNA expression levels determined that IL-10 mRNA was significantly elevated in the grade I NF2 negative meningioma tissues." (PMID 32070062, 2020). "Additionally, we investigated the presence of miR-21 and the different cytokines: Interleukin-6 and Interleukin-10 (IL-6 and IL-10), Granulocyte-Macrophage Colony-Stimulating Factor (GM-CSF) and Chemokine (C-C motif) Ligand 2 (CCL2) in the plasma of 28 patients diagnosed with meningioma." (PMID 38259646, 2023). "Although activated M2 macrophages have not been assessed in meningiomas, other brain tumours such as gliomas, glioblastomas and numerous other disease models have been shown to produce signature cytokines such as TNF-alpha, TGF-beta, IL-6 and IL-10." (PMID 32070062, 2020).
Myalgia (5 papers, 2012 to 2026). "Arthralgia was associated with high IL-4 levels (p = 0.0388), whereas myalgia was linked to increased IL-10 levels (p = 0.0114)." (PMID 37235332, 2023). "Moreover, arthralgia and myalgia in our patients were linked to increases in IL-4 (p = 0.0388) and IL-10 (p = 0.0114), respectively." (PMID 37235332, 2023). "Diminished levels of IL-10 expression were observed in Pool Spike CoV-2-stimulated-Tregs compared with that of Pool CoV-2-stimulated Tregs in volunteers who had not developed myalgia, diarrhea, or anosmia during acute disease." (PMID 36969257, 2023). "The Pool Spike CoV-2-stimulated samples of Mild Recovered volunteers who had not developed myalgia, fatigue, or nasal obstruction presented lower IL-10+ Treg frequency than did the unstimulated cells." (PMID 36969257, 2023).
Mycobacterium infection (5 papers, 2014 to 2023). Infections with bacteria of the genus Mycobacterium. "Radix Paeoniae Rubra extracts has been shown to inhibit the expression of IL-10, and can reduce the reactivation of TB and higher mycobacterial burden, thereby reducing the susceptibility to Mycobacterium infection." (PMID 26198726, 2015). "IL-10 is an anti-inflammatory cytokine produced by macrophages and T-cells during Mycobacterium infection." (PMID 26198726, 2015). "Moreover, it is reported that IL-10 secreting transgenic mice were unable to clear the infection and developed bacterial burden after being challenged with BCG (Mycobacterium bovis), suggesting that IL-10 help in mycobacterial infection." (PMID 27905994, 2016).
mycoplasma infections (5 papers, 2016 to 2025). "Increased levels of IL10 have been associated with mycoplasma infections and this is believed to have a role in the pathogenesis of mycoplasmosis, most likely by inducing immunosuppression." (PMID 40635092, 2025). "The involvement of IL-10 in mycoplasma infections in sheep and goats has been elucidated, and its anti-inflammatory nature has been reported." (PMID 36014052, 2022). "However, mycoplasma infections are not necessarily related to strong inflammatory responses, because LAMPS can suppress inflammation by inducing IL-10 production." (PMID 32456681, 2020).
osteomyelitis (5 papers, 2020 to 2025). An acute or chronic inflammation of the bone and its structures due to infection with pyogenic bacteria. "Decreased levels of IL-10 have also been associated with osteomyelitis in patients suggesting a protective role of IL-10." (PMID 40903786, 2025). "Recent investigations have uncovered a correlation between IL-10 SNPs and a spectrum of inflammatory disorders, such as sepsis, osteomyelitis, and pancreatitis." (PMID 39301021, 2024). "Simultaneously, serum samples of S. aureus induced osteomyelitis rats were collected to assay the concentration of TNF-α and IL-10 at 1, 2, 3, 5, and 7 days through enzyme-linked immunosorbent assay (Elisa)." (PMID 36109760, 2022). "These cumulative findings suggest that IL-10 SNP rs1800871, through its ability to modulate IL-10 levels and further influence the activation of the NLRP3 inflammasome, may exert an influence on the progression of osteomyelitis." (PMID 39301021, 2024).
Pancytopenia (5 papers, 2015 to 2021). An abnormal reduction in numbers of all blood cell types (red blood cells, white blood cells, and platelets). "In future, cytokine measurements such as IL-6 and IL-10 may become one of the factors elucidating the mechanisms of immune reaction that results in pancytopenia." (PMID 27885344, 2016). "Pancytopenia and significantly serum cytokines level rise were observed, including IFN‐γ, IL‐6, and IL‐10." (PMID 31050207, 2019).
polycystic ovary syndrome (5 papers, 2020 to 2025). A disorder that manifests as multiple cysts on the ovaries. "Such susceptible individuals may include those with polycystic ovary syndrome (PCOS), endometriosis, disrupted gastrointestinal motility, as well as people carrying genetic defects (e.g., IL-10 or HNF4A deficiency)." (PMID 41488633, 2025).
Prostate tumor (5 papers, 2003 to 2026). "Since TIMP-1 overexpression has been associated with the blockade of metastasis in human prostate tumour xenograph model studies, we suggest that IL-10 may indirectly prevent tumour metastasis by this mechanism." (PMID 12771930, 2003). "Another study showed that IL-10 stimulated TIMP-1 secretion and inhibition of MMP-2, 9 by prostate tumor cells." (PMID 33841538, 2020). "Distinctly, IL-10 has been shown to stimulate TIMP-1 secretion and inhibit the secretion of MMP-2 and MMP-9 by prostate tumor cells." (PMID 33841538, 2020).
protozoal infections (5 papers, 2008 to 2024). "The inflammatory response may be the initial host response against protozoal infection or may be due to reduction in IL-10 levels." (PMID 38521853, 2024). "Although IL-10 can be produced by a variety of CD4 T-cell subsets, IL-10 production by using the Th1 subset has been shown to be required for attenuation of morbidity and immune-mediated pathology during primary murine malaria infection and other protozoal infections." (PMID 29097996, 2017). "In other protozoal infections of mice CD4+ effector T cells that co-produce IFN-γ and IL-10 have been identified." (PMID 19343213, 2009).
pyometra (5 papers, 2015 to 2025). "(2014), TNF‐α, IFN‐γ, IL‐2, IL‐4 and IL‐10 cytokine concentrations were found to be high in dogs with pyometra." (PMID 39792082, 2025). "Overall, transcription levels of pro-inflammatory cytokines IL-1β, IL-6 and IL-8, and of anti-inflammatory cytokines IL-10 and TGFβ were significantly higher (p < 0.0001) in pyometra endometria than in healthy diestrous endometria." (PMID 27829462, 2016). "Before surgery, bitches with pyometra had higher serum concentrations of IL-6 and IL-10 (149.4 (120.2–179.5) pg/ml and 53.9 (34.1–73.3) pg/ml, respectively) than the controls [1.8 (1.8–2.0) pg/ml and 21.2 (19.5–28.2) pg/ml] (P < 0.001 for both IL-6 and IL10)." (PMID 26410584, 2015). "An increase in serum concentrations of IL-6 and IL-10 was present before surgery in bitches with pyometra and 3 days after ovariohysterectomy in healthy controls." (PMID 26410584, 2015). "The levels of IL6 and IL10 decreased significantly in the bitches with pyometra on days 3 and 10 after surgery as also reported by others." (PMID 26410584, 2015). "In conclusion, an increase in serum concentrations of IL-6 and IL-10 occurred before surgery in bitches with pyometra and 3 days after OHE in healthy control bitches undergoing elective OHE." (PMID 26410584, 2015). "The aim of the study was to assess changes in serum interleukin (IL)-6 and IL-10 concentrations in bitches with pyometra undergoing ovariohysterectomy." (PMID 26410584, 2015). "For this reason, the aim of the study was to assess concentrations of serum IL-6 and IL-10 in bitches with pyometra undergoing ovariohysterectomy (OHE) and compare these finding to healthy bitches undergoing elective OHE." (PMID 26410584, 2015). "Before surgery, bitches with pyometra had significantly higher serum concentrations of IL-6 and IL-10 than the controls." (PMID 26410584, 2015). "Based on our result we suggest, that production of IL-6 and IL-10 is upregulated in bitches having pyometra." (PMID 26410584, 2015). "The increase in IL-10 in the context of pyometra in cats may suggest a tissue response to the increase in pro-inflammatory cytokines, aiming to reestablish the local immune microenvironment and prevent damage caused by an exacerbated inflammatory environment." (PMID 39457917, 2024). "Thus we hypothesized that in cases of canine pyometra alterations in IL-6 and/or IL-10 could be present." (PMID 26410584, 2015). "Compared to the presurgery concentration bitches with pyometra had decreased serum concentration of IL-6 and IL-10 3 days after OHE (P < 0.01 and P < 0.05, respectively) and 10 days after OHE (P < 0.01 for both IL6 and IL10)." (PMID 26410584, 2015). "However, in another study, no increase in these cytokines (TNF‐α and IL‐10) was observed in dogs with pyometra." (PMID 39792082, 2025).
status epilepticus (5 papers, 2011 to 2023). Status epilepticus is defined as a continuous seizure lasting more than 30 min, or two or more seizures without full recovery of consciousness between any of them. "An unexpected finding in the present study was that knock-out of the P2X7R was associated with higher release of cytokines post-status epilepticus, including both pro- and anti-inflammatory cytokines (e.g., IL-10, IL-12p70, IL-27/30, IL-4, KC/GRO MIP-1α, MIP-2, TNF-α)." (PMID 34572093, 2021). "Both microglial pro-inflammatory cytokines (IL-1β and TNF-α) and anti-inflammatory cytokines (IL-4 and IL-10) showed increased expression after pilocarpine-induced status epilepticus, indicating a complex role of microglia in the epileptic brain." (PMID 34924959, 2021). "The expression levels of microglial pro-inflammatory cytokines (TNF-α and IL-1β) and anti-pro-inflammator cytokines (IL-10 and IL-4) increase in brain after status epilepticus." (PMID 34924959, 2021). "The mean IL-10 level of afebrile controls was 2.7 pg/mL, that in febrile controls was 8.3 pg/mL, and that in afebrile status epilepticus attacks in intractable epilepsy patients was 0.6 pg/mL." (PMID 21989210, 2011). "Afebrile seizure patients and afebrile status epilepticus patients with intractable epilepsy showed significantly decreased IL-10 levels than that of febrile and afebrile controls (2.6 pg/mL & 0.6 pg/mL, p < 0.05)." (PMID 21989210, 2011). "The dynamic linkage between interleukin-10 (IL-10) level,as a cytokine, and miR-187 level,as a post-transcriptional inflammation-related miRNA, has been evaluated in the hippocampus of a rat model of status epilepticus and patients with temporal lobe epilepsy." (PMID 37727513, 2023). "The aim of the present study was to investigate the dynamic expression pattern of interleukin (IL)-10 as an anti-inflammatory cytokine and miR-187 as a post-transcriptional inflammation-related miRNA in the hippocampus of a rat model of status epilepticus (SE) and patients with TLE." (PMID 26696826, 2015).
Streptococcus pneumonia (5 papers, 2019 to 2024). "The RYNM exhibited its therapeutic effects on Streptococcus pneumonia mainly via the regulation of cell proliferation and survival through the IL-6/IL-10/IL-17, Bax/Bcl-2, COX-1/COX-2, NF-κB and TNF-α signalling pathways." (PMID 33678123, 2021).
subarachnoid hemorrhage (5 papers, 2017 to 2025). A serious neurological disorder characterized by intracranial hemorrhage into the subarachnoid space. "Aneurysmal subarachnoid hemorrhage induced systemic IL-10 release." (PMID 32106601, 2020). "Summary of IL-10 subarachnoid hemorrhage preclinical studies." (PMID 28659854, 2017). "Comparatively, conclusive studies investigating the contribution of IL-10 in subarachnoid hemorrhage are lacking." (PMID 28659854, 2017).
thalassemia (5 papers, 2013 to 2022). An inherited blood disorder characterized by a decreased synthesis of one of the polypeptide chains that form hemoglobin. "Analysis of cytokines showed a wide variability of the IL-6 and IL-10 values both in the group of total thalassemia patients (THAL) and in healthy subjects (CTR), with extremely high values of IL-6 in some patients." (PMID 36699704, 2022). "IL-10 was found to be increased in thalassemia patients with a possible role in the inhibition of erythropoiesis and in the induction of anemic crisis in these patients." (PMID 36699704, 2022). "In thalassemia patients η1and η1/η200 correlated positively with the cytokines IL-6 and IL-10 (p < 0.001), and negatively with the adhesion molecule L-selectin (η1, p < 0.05; η1/η200, p < 0.05)." (PMID 36699704, 2022). "TNF-α and IL-10 were found to be elevated in iron overloaded patients with thalassemia major." (PMID 25822525, 2015). "Serum 8-isoprostane, TNF-alpha, IL-10, 24-hour ECG monitoring, echocardiograms and the incidence of thalassemia-related complications were collected." (PMID 32547310, 2020). "This is because it is believed that patients with thalassemia have increased plasma malondialdehyde and circulating non-transferrin bound iron (NTBI) relative to patients with SCD, and lower levels of some cytokines (interleukin 5 and interleukin 10) and γ-tocopherol." (PMID 34760898, 2021).
Toxocara infection (5 papers, 2012 to 2025). "Second, immunological phenomena, such as IL-10 production, that is induced by the Toxocara infection could break the association between sIgE and SPT." (PMID 23133689, 2012). "In contrast, in toxocariasis, Th2 cells are involved; they secrete IL-4, IL-5, IL-9, IL-10, and IL-13 and promote type 2 immunity, characterized by high antibody titers." (PMID 40943043, 2025). "The production of the hallmark regulatory cytokines IL-10 and TGF-β after contact with TES or mucins again implies the role of Treg cells in Toxocara infection." (PMID 26044883, 2015). "Moreover, increased IL-10 expression is another contributor to the development and extension of toxocariasis pathology." (PMID 37874393, 2023). "BMMSCs enhance the release of IL-10 cytokine by Treg cells in Toxocara infection." (PMID 33776300, 2021).
upper respiratory tract infection (5 papers, 2017 to 2025). "There are reports on genetic susceptibility for other recurrent infections such as upper respiratory tract infections and genital chlamydia infection, in which the same immunogenetic factors as reported for HZ occurrence (IL-10 polymorphism) were implicated." (PMID 28486993, 2017). "However, a previous study in physically active participants reported that a high IL-10-stimulated production was a risk factor for the development of upper respiratory tract infection (URTI)." (PMID 35011664, 2021). "reduce IFNγ & TNF-α and increase IL-4 & IL-10 secretions to control the immunostimulatory effects in upper respiratory tract infection." (PMID 39294611, 2024).
Achalasia (4 papers, 2015 to 2024). A disorder of esophageal motility characterized by the inability of the lower esophageal sphincter to relax during swallowing and by inadequate or lacking peristalsis in the lower half of the body of the esophagus. "The myenteric plexus of esophageal biopsies obtained from achalasia patients had a higher relative IL-10-producing B-cell percentage when compared with tissues from control group." (PMID 26078981, 2015). "Genetic risk factors within the HLA-DQ receptor, SNPs on the IL23R which regulates T cell differentiation, on PTPN22, which is a down-regulator of T-cell activation, and IL10 gene promoter were identified, emphasizing the concept of a genetically driven immune response in patients with achalasia." (PMID 39337632, 2024). "Finally, only IL-10 was significantly increased in achalasia patients." (PMID 38267468, 2024). "Subsequently, a panel of eleven SNPs in the IL33, IL1RL1, IL23R and IL10 genes was analyzed in an Italian cohort, using TaqMan genotyping assays, reporting significant differences in allele and genotype frequencies of the rs3939286 variant of the IL33 gene between achalasia patients and controls." (PMID 39337632, 2024). "Patients with achalasia had increased circulating CD4+ T cells, CD25- T cells, CD161+ T cells, FOXP3+ Tregs, IDO-expressing regulatory plasmacytoid dendritic cells (pDCregs), and IL-10-expressing regulatory B cells (Bregs) compared to healthy individuals." (PMID 38267468, 2024).
allergic contact dermatitis (4 papers, 2014 to 2025). An inflammatory skin condition caused by an immune response to direct contact between the skin and an allergen. "With this background, this research was conducted to investigate the association between circulating IL-10 levels and vitamin D status in patients with allergic contact dermatitis following exposure to parthenium." (PMID 40630332, 2025). "We have shown that MC-derived IL-10 can curtail inflammation associated with certain settings of allergic contact dermatitis and low-dose UVB irradiation of the skin." (PMID 25340820, 2014). "Though allergic contact dermatitis has been mainly associated with Th1/Th17 phenotypes, Th2-type regulatory cytokines such as IL-10 may have an important role in the downregulation of contact hypersensitivity reactions." (PMID 25183967, 2014). "Therefore, decreased IL-10 concentrations, found in this and some previous studies, might indicate the utilization of this cytokine in downregulation of allergic contact dermatitis." (PMID 25183967, 2014). "Heat-killed Lactobacillus acidophilus strain L-92 produced higher levels of Foxp3, IL-10 and TGF-β compared to control mice and suppresses allergic contact dermatitis." (PMID 27175277, 2016).
astrocytoma (4 papers, 2017 to 2025). "In one study, 87.5% of grades III and IV astrocytomas expressed IL-10 mRNA compared to 4% of grade II astrocytomas." (PMID 28346397, 2017). "The influence of CAPE on the secretion of cytokines (IL-8, IL-10, IL-26), metalloproteinases (MMP-1, -2, -3), and pentraxin-3 (PTX3) was assessed in CCF-STTG1 astrocytoma cells stimulated with LPS and/or IFN-α under normoxic and hypoxic conditions." (PMID 41515435, 2025). "While we did not detect differences in mRNA levels of interleukin-10 (IL-10), protein levels were highly abundant in high-grade astrocytoma (33.7 ± 12 pg/mL; **P < .01)." (PMID 34131649, 2021).
autoimmune hemolytic anemia (4 papers, 2009 to 2018). Autoimmune hemolytic anemia (AIHA) is an autoimmune disorder in which various types of auto-antibodies are directed against red blood cells causing their survival to be shortened and resulting in hemolytic anemia. "Previously, we have shown that IL-10 and peptides containing a dominant T cell epitope from red cell band 3 modulate autoimmune hemolytic anemia in NZB mice." (PMID 28455817, 2017).
benign ovarian tumor (4 papers, 2015 to 2024). "A previous smaller study found higher levels of IL-10 in OC compared to benign ovarian tumor or normal tissue." (PMID 39199610, 2024). "The immunosuppressive role of IL-10 in OC is well documented, with OC patients showing elevated IL-10 levels in sera in comparison with healthy controls and women with benign ovarian tumours." (PMID 28410380, 2017). "To elucidate which factors present in ascites distinguish the malignant OC environment from the environment of benign ovarian tumours, we investigated which proteins in addition to IL-10 in ascites exerted a suppressive influence on TLR-mediated DC activation." (PMID 28410380, 2017).